RARB (retinoic acid receptor beta)
Diseases named in the same sentence as RARB in open-access papers (continued):
Sharing a sentence is not in itself a finding about the gene and the disease.
prostate carcinoma (continued). "That gene expression regulated by RARγ or RARβ might be more necessary to the growth of prostate carcinoma cells than their normal counterparts remains an interesting possibility." (PMID 15266311, 2004). "In addition, RARβ overexpression was shown to reduce prostate cancer cell proliferation." (PMID 31212954, 2019). "For example, researchers can rapidly detect fluctuations in prostate cancer-related epigenetic biomarkers (RASSF1, APC, and RARb gene hypermethylation) before and after drug administration." (PMID 37304140, 2023). "For example, the integrated analysis function of the prostate cancer organoids-on-a-chip can rapidly detect fluctuations in prostate cancer-related epigenetic biomarkers (RASSF1, APC, and RARb gene hypermethylation) before and after drug administration." (PMID 37304140, 2023). "selected epigenetically altered genes in prostate cancer and found AR, GSTP1, RARB, SPARC, TIMP3, and NKX2-5 to be hypermethylated in AA patients." (PMID 36937425, 2023). "We included primers for four genes in the pre-amplification pool (RASSF1, APC, RARB and GSTP1), which have previously been identified as being methylated in a large percentage of prostate cancers." (PMID 35272673, 2022). "GE can reverse DNA hypermethylation and reactivates p16INK4a, RARb and MGMT in KYSE 510 esophageal squamous cell carcinoma cells, KYSE 150 cells, prostate cancer LNCaP and PC3 cells." (PMID 31030484, 2019). "The current literature on the functions of NRs in prostate cancer indicate that DAX1, SHP, RARβ/γ, FXRs, LXRs, VDR, ERβ, ERRβ/γ, and MR can play antioncogenic roles, while PPARγ, RORγ, SF-1, LRH-1, Erα, and GR, as well as AR, can play oncogenic roles." (PMID 31212954, 2019). "We identified five highly methylated genes in prostate cancer: GSTP1, RARB, RASSF1, SCGB3A1, CCND2 (P < 0.0001), with an area under the ROC curve varying between 0.89 (95 % CI 0.82–0.97) and 0.95 (95 % CI 0.90–1.00)." (PMID 27576364, 2016). "Our preliminary results highlighted that hypermethylation of GSTP1, RARB, RASSF1, SCGB3A1 and CCND2 was highly tumour-specific in prostate cancer tissue." (PMID 27576364, 2016). "Our preliminary results, obtained in a single-institution study with limited enrolment, showed that the hypermethylation of GSTP1, RARB, RASSF1, SCGB3A1 and CCND2 was highly tumour-specific in prostate cancer tissue." (PMID 27576364, 2016). "Evidence from earlier studies has linked promoter hypermethylation of specific genes to pathogenesis and tumor progression in prostate cancer, e.g. APC, RARβ, and GSTP1." (PMID 24626295, 2014). "Several are known biomarkers for diagnosis and prognosis of prostate cancer (APC, GSTP1, KIT, PYCARD, PGDGRB, RARB, RARRES1, and TIMP1) and some though not biomarkers, were found to be dysregulated in the disease (CDKN1B, MMP7, and MMP9)." (PMID 24626295, 2014). "In prostate cancer, numerous hypermethylated genes have been found, with GSTP1, APC1 and RARB amongst the most frequently reported, and hitherto mainly assessed for diagnostic purposes." (PMID 25193387, 2014). "Retinoic acid receptor beta (RARβ) and PDLM4 have been shown to function as tumor suppressor genes in human prostate cancer cell and xenograft models." (PMID 22191037, 2011). "Genistein also induced promoter hypomethylation and reactivated the expression of tumor suppressor genes GSTP1, EPHB2, p21, RARβ, p16INK4a, and MGMT in breast cancer, kidney cancer, esophageal squamous cell carcinoma, and prostate cancer cell lines, leading to cell cycle arrest and cell death." (PMID 32878338, 2020). "In addition to many novel candidates, this list contained several genes known to be frequently hypermethylated in prostate cancer (e.g. GSTP1, RARB), supporting the validity of our results." (PMID 28052017, 2017). "RARβ and PDLM4 promoters are commonly hypermethylated during prostate cancer progression." (PMID 22191037, 2011).
prostate carcinoma (continued). "Hypermethylation of the CCND2 promoter is significantly higher in prostate cancers compared to normal prostate tissues (32%, 6% resp.; P = 0.004), and there are statistically significant concordances between methylation of CCND2 and the methylation of RARβ, GSTP1, CDH13, RASSF1A, and APC genes." (PMID 22191037, 2011).
cervical carcinoma (19 papers, 2007 to 2026). A carcinoma arising from either the exocervical squamous epithelium or the endocervical glandular epithelium. "RARB methylation showed the strongest association with cervical cancer compared to other genes (OR = 15.25; 95% CI: 6.06–40.0; P < 0.001)." (PMID 33718129, 2021). "Cervical cancer and promoter methylation of RARB and DAPK1 genes were associated with increasing age (OR = 1.12; 95% CI: 1.01-1.26; P = 0.037 and OR = 1.05; 95% CI: 1.00-1.10; P = 0.040)." (PMID 33718129, 2021). "This research highlights BIRC5, HOXA1, and RARB as significant therapeutic targets in cervical cancer due to their critical involvement in its development." (PMID 40564176, 2025). "Through this analysis, certain genes, including BIRC5 (survivin), HOXA1, and RARB, were identified as highly relevant in cervical cancer due to their topological properties and high scores in databases like Genecards." (PMID 40564176, 2025). "Specifically, we characterized aberrantly methylated host promoter genes (RARB, CADM1, DAPK1, and PAX1) and their possible association with: invasive cervical cancer, cervical cancer stage, HIV status, age, high-risk HPV genotypes." (PMID 33718129, 2021). "RARB is involved in cell proliferation and is usually methylated in several cancers including cervical cancer." (PMID 31766427, 2019). "Pyrosequencing analysis confirmed earlier studies indicating that DAPK1, SLIT2, WIF1 and RARB genes are common targets for aberrant methylation in cervical cancer." (PMID 25826459, 2015). "Herein, we identified an epigenetic biomarker panel (DAPK1, SLIT2, WIF1 and RARB) that distinguished cervical cancers from normal cytology samples." (PMID 25826459, 2015). "We are limited by the lack of data on squamous cervical cancer antigen to know the association with RARB protein expression." (PMID 33718129, 2021). "Moreover, we found that cervical cancer stage was influenced by RARB (χ2= 7.32; P = 0.002) and CADM1 (χ2=12.68; P = 0.013) hypermethylation, and HIV status (χ2= 19.93; P = 0.001)." (PMID 33718129, 2021). "RARB promoter methylation has been shown to be an early event in multistage cervical carcinogenesis with overall high frequencies of promoter methylation reported in cervical cancer specimens." (PMID 33718129, 2021). "Furthermore, curcumin-induced promoter DNA hypomethylation was associated with the reactivation of tumor suppressor genes such as p15INK4B in acute myeloid leukemia and RARβ in lung cancer and cervical cancer cell lines." (PMID 32878338, 2020). "Meanwhile, correlated with clinical parameters, promoter hypermethylation and expression loss of PARK-2, RARβ, and FHIT are significantly higher in cervical cancer than in CINs and normal tissues, resulting in a significant association with tumor stage and histological grade." (PMID 29850477, 2018). "In our study, RARB methylation was very low in normal tissue and ranged from <1% to 59% in cancers, consistent with previously studies that established a high prevalence of RARB methylation in cervical cancer." (PMID 25826459, 2015). "In another study, the miRNAs, miR-203 and miR-30b and the target genes BIRC5, HOXA1, and RARB were suggested to be critical players in the pathogenesis of cervical cancer, as revealed by the systematic analysis of dysregulated miRNAs and their targets in cervical cancer." (PMID 30020984, 2018). "Our data further confirm the possible role of promoter methylation of RARB, CADM1, DAPK1, and PAX1 in cervical cancer tumorigenesis." (PMID 33718129, 2021). "In the cervical cancer (HELA) cell line, EGCG (25 μM) suppressed DNMT3B activity and expression, leading to promoter hypomethylation and the reactivation of RARβ, CDH1, and DAPK1." (PMID 32878338, 2020).
cervical carcinoma (continued). "The expression of E-cadherin, DAPK1, RARβ, p16INK4a, MGMT, FHIT, RUNX3, CDH1, PTEN, and SOC51 was also reactivated through genistein-induced promoter hypomethylation in cervical cancer cells." (PMID 32878338, 2020). "Combining parallel testing of PAX1, DAPK1, RARB, WIF1, and SLIT2 DNA methylation and HPV DNA increases specificity to identify cervical cancer and achieves better precision than single HPV DNA testing does." (PMID 29850477, 2018). "We confirmed that DAPK1, RARB, SLIT2, and WIF1 are aberrantly methylated in cervical cancer compared to normal tissue, whereas, APC, CDH1 and FHIT are less commonly methylated." (PMID 25826459, 2015). "The remaining genes (DAPK1, RARB, SLIT2 and WIF1) were evaluated for their ability to identify cervical cancer cases in relation to HPV infection and age." (PMID 25826459, 2015). "The high frequencies of hypermethylation in RARB (40% vs. 38%), CADM1 (50% vs. 44%), and DAPK1 (33% vs. 19%) were shared between HPV-positive OPSCC and cervical cancer." (PMID 25065733, 2014). "In addition, this study further substantiated the previous studies results of overall high frequency of methylation rate in promoter regions of RARB, CADM1, DAPK1, and PAX1 genes in cervical cancer subjects." (PMID 33718129, 2021). "Therefore, our study aimed to characterize methylation status of four host genes (RARB, CADM1, DAPK1, and PAX1) that have been studied to a great extent in relation to cervical cancer." (PMID 33718129, 2021). "Alterations in DNA methylation of specific genes in cervical cancers, such as DAPK1, RARB, WIF1, and SLIT2, may also occur early in cervical carcinogenesis and should be evaluated." (PMID 25826459, 2015). "Prominent alterations in DNA methylation in cervical cancers, such as shown for DAPK1, SLIT2, WIF1 and RARB, may also be early molecular events in cervical carcinogenesis and using the pyrosequencing assays developed here should be further tested in CIN3 lesions." (PMID 25826459, 2015). "Notably, all eight genes that were frequently methylated in the HPV-transfected cell lines and cervical cancer cell lines (i.e. TP73, ESR1, RARβ, DAPK1, MGMT, CADM1, CDH13 and CHFR) overlapped with those found to be methylated in the cervical carcinoma specimens." (PMID 17971771, 2007). "We observed a significant higher frequency of subjects having promoter methylation signals at the four genes, RARB (94.0%), CADM1 (76.5%), DAPK1 (64.1%), and PAX1 (96.5%), in patients with invasive cervical cancer compared to the subjects without cancer." (PMID 33718129, 2021). "Other genes reportedly hypermethylated in cervical cancer with little to no methylation in normal or low-grade CINs include DAPK1, RARB, TIMP3, CCNA and FHIT." (PMID 25826459, 2015).
melanoma (15 papers, 2002 to 2025). A malignant, usually aggressive tumor composed of atypical, neoplastic melanocytes. "One of the recurrent epigenetic targets in melanoma is RARB encoding retinoic acid receptor beta (RARβ), which is silenced by promoter hypermethylation in 45-70% of cutaneous melanomas." (PMID 29137417, 2017). "In accordance with previous findings, ATRA increased the expression of p14ARF in RARβ-positive melanoma cells." (PMID 29137417, 2017). "In melanoma cells harboring the BRAFV600E mutation, RARβ activation antagonized the effect of the BRAF inhibitor PLX4032 (vemurafenib)." (PMID 29137417, 2017). "To further study the role of RARβ signaling in melanoma, we selected four RARβ-positive melanoma cell lines (ED-007, ED-027, ED-117 and ED-196) for functional analysis." (PMID 29137417, 2017). "Contrary to the situation in primary melanocytes, blocking RARβ signaling in melanoma cells led to energetic stress, as indicated by activation of AMPK." (PMID 29137417, 2017). "RARB is silenced by promotor hypermethylation in many melanomas, suggesting that it possesses tumor-suppressive properties." (PMID 29137417, 2017). "To extend these data, we examined RARβ expression in 84 of these melanoma cell lines as well as in human epidermal melanocytes." (PMID 29137417, 2017). "In melanoma cells, inhibition of RARβ promoted lower mitochondrial respiration and higher glycolytic activity, which led to energetic stress and activation of the energy sensor AMP-activated protein kinase." (PMID 29137417, 2017). "Inhibition of differentiation during the progression of CD133-expressing melanoma stem cells may therefore be mediated by downregulation of RARB, TYRP1, and TYRP2, among other mechanisms." (PMID 38727313, 2024). "In conclusion, we identified a novel function of RARβ signaling in melanocytic and melanoma cell metabolism, which could have clinical implications." (PMID 29137417, 2017). "The selective advantage of losing RARβ function in melanoma, for example by RARB hypermethylation, could relate to the transition to a more glycolysis-dependent phenotype supporting the Warburg effect." (PMID 29137417, 2017). "In melanoma cells, activation of RARβ antagonizes the effect of PLX4032, whereas inhibition of RARβ induces glycolytic dependence and energetic stress, making the cells vulnerable to treatment with the pyruvate dehydrogenase kinase inhibitor dichloroacetate (DCA)." (PMID 29137417, 2017). "Collectively, these data suggest that RARβ signaling is involved in regulating cellular metabolism in melanoma and may provide a potential target in combination treatment strategies." (PMID 29137417, 2017). "Finally, we have demonstrated that a combination of a selective rexinoid and retinoid agonists has an additive effect on growth inhibition of a melanoma cell line expressing RARβ and RXRγ." (PMID 19267912, 2009). "Thus, ATRA might reduce the sensitivity of RARβ-positive melanomas to PLX4032 by limiting the cytotoxicity from ROS production." (PMID 29137417, 2017). "However, blocking RARβ signaling promotes glycolytic dependence in melanoma cells and enhances the effect of DCA, which could potentially be exploited therapeutically." (PMID 29137417, 2017). "We previously found that the ability of RA to increase RARβ and PKCα expression in A-fos expressing clones was normal, suggesting that A-fos and inhibition of AP-1 activity interferes with a down-stream, later event in the RA induction of differentiation and growth arrest in B16 melanoma cells." (PMID 18269766, 2008). "For example, berberine can suppress EMT in melanoma cells by regulating cross-talk between PI3K/AKT and RARα/RARβ signaling." (PMID 31772677, 2019). "To further study the effect of RARβ inhibition on melanoma metabolism, we measured OCR and ECAR in RARβ-positive melanoma cell lines treated with LE135." (PMID 29137417, 2017).
melanoma (continued). "The observation of the bona fide TSGs affected by promoter hypermethylation in CMM suggests that these molecules, e.g., TCF21, SOCS, RUNX, RASSF6, RASSFA, RARβ, MAPK13, H- and E-cadherin and AGTR, are a candidate for the design of new therapeutic strategies for human melanoma." (PMID 34639015, 2021). "Retinoic acid receptor beta (RARβ) is epigenetically silenced in a large proportion of melanomas, but a link between RARβ and metabolic rewiring of melanoma has not been established." (PMID 29137417, 2017).
neuroblastoma (14 papers, 2004 to 2025). Neuroblastoma (NB) is the most common solid, extracranial childhood tumor. "Third, they tested the ability of the substances to induce RARβ expression, which is reportedly associated with favorable clinical outcomes in neuroblastoma, as described in the previous section." (PMID 38339295, 2024). "Indeed, it has been demonstrated that TLR3 activation by Poly(I:C) synergizes with 13-cis-retinoic acid in the treatment of high-risk neuroblastoma, through the activation of retinoic acid receptor beta (RARβ)." (PMID 33147700, 2020). "However, high RARβ expression was associated with good outcomes in patients with neuroblastoma, and overexpression of the gene by transfection appeared to increase the responsiveness of some neuroblastoma cell lines to RA." (PMID 38339295, 2024). "RNA sequencing results showed a synergistic induction of genes associated with RA signaling (RARB, RARG), neuronal differentiation (HOXC5, PBX1), and chromatin remodeling (RYBP, JADE2), which are positively correlated with favorable prognosis in neuroblastoma." (PMID 39711563, 2024). "RARβ is an ATRA-inducible tumor suppressor that plays an important role in neuroblastoma cell differentiation." (PMID 22087283, 2011). "In addition, the Ch-IP assay showed that c-Jun bound to RARβ, TrkB and PDGFRα promoters, which are crucial to RA-induced neuroblastoma cell differentiation." (PMID 40149013, 2025). "It does however appear to inhibit apoptosis of neuroblastoma cells, via an interaction with RARβ." (PMID 27611191, 2016). "CDKN1A is induced by RA through RARB in human neuroblastoma tumors." (PMID 15345368, 2004). "Several of the investigated TSGs have chromosomal locations that are recurrently lost in neuroblastoma: TP73 on 1p, BLU, RARB and RASSF1A on 3p, and PTEN on 10q." (PMID 22984959, 2012).
non-small cell lung carcinoma (13 papers, 2004 to 2023). A group of at least three distinct histological types of lung cancer, including non-small cell squamous cell carcinoma, adenocarcinoma, and large cell carcinoma. "One of the effector genes of RAR and RXR is Retinoic acid receptor beta (RARβ), which is a tumor-suppressor gene, and its methylation has been associated with breast, cervical and Non-Small Cell Lung Cancer." (PMID 35406744, 2022). "Known modifications of RARB include hypermethylation of the gene promoter or loss of 3p chromosome as in the case of non-small cell lung carcinoma." (PMID 27011326, 2016). "RARβ is a tumor-suppressor gene silenced by epigenetic mechanisms such as DNA methylation in breast, cervical and non-small cell lung cancers." (PMID 35406744, 2022). "In conclusion, we identified significant associations between seven genes (CDKN2A, RASSF1, MGMT, RARB, DAPK, WIF1 and FHIT) and smoking behavior in non-small cell lung cancer patients." (PMID 25754026, 2015). "Induced RARβ expression sensitizes non-small cell lung cancer cells and colorectal cancer cells to the anticancer effects of retinoids." (PMID 18166136, 2007).
breast tumors (12 papers, 2007 to 2021). "The importance of the loss of RARβ expression in breast tumor was explained in the paper of Lin and colleagues, and correlated with AP-1 over-expression." (PMID 32012980, 2020). "Confirmation about the loss of RARβ expression in breast tumor tissues comes from two different papers." (PMID 32012980, 2020). "Retinoic acid receptor β expression deficiency and inadequate responsiveness of retinoids via RARβ may reduce the treatment efficacy in patients with advanced breast tumours." (PMID 24720764, 2014). "This RNA was extracted from an additional n = 27 breast tumours, n = 20 fibroadenoma and n = 15 normal breast tissues was quantified by RQ-PCR targeting RARβ and THRα." (PMID 25934412, 2015). "Recently, our laboratory, in accordance with other authors, has shown that RARβ methylation in primary breast tumours correlated with lymph node invasion and metastasis." (PMID 24720764, 2014). "In the second paper, the in situ hybridization failed to found RARβ in breast tumor tissue and normal adjacent tissues, and found it only in normal tissues distant from the tumor sites." (PMID 32012980, 2020).